LRP8 (LDL receptor related protein 8)
Diseases named in the same sentence as LRP8 in open-access papers (continued):
Sharing a sentence is not in itself a finding about the gene and the disease.
cardiovascular disease (8 papers, 2012 to 2025). "Low-density lipoprotein receptor-related protein 8 (LRP8) or Apolipoprotein E receptor 2 (ApoER2), is expressed by macrophages, endothelial cells and platelets and has been implicated in the development of cardiovascular diseases." (PMID 32664652, 2020). "The eight significant SNPs identified in Model 1 are located in five genes —LRP8, CAPN13, MITF, SGCD and MLL3—previously implicated in BP variation or cardiovascular disease." (PMID 28002425, 2016).
infection (8 papers, 2015 to 2025). The state of being infected such as from the introduction of a foreign agent such as serum, vaccine, antigenic substance or organism. "First, while soluble LRP8 decoys show prophylactic efficacy, genetic evidence from conditional LRP8 knockout models is needed to confirm its physiological role in natural infection." (PMID 41461646, 2025).
neurodegenerative disease (1 paper, 2023). A disorder of the central nervous system characterized by gradual and progressive loss of neural tissue and neurologic function. "Importantly, all of these synaptic regulators (Nos1, Lrp8, Argef2, Sema5b) and other significantly altered splice variants (e.g., Adipor2, Mapk14, Smarca4, Sort1, Mapt) have been linked to AD and other neurodegenerative diseases." (PMID 37819053, 2023).
LRP8 also shares sentences with these, for which no sentence is quoted: coronary artery disease (8 papers); cognitive deficits (7); bipolar disorder (5); depression (4); epilepsy (4); Obesity (4); gastric cancer (3); viral infection (3); aortic aneurysm (2); brain disorder (2); hyperplasia (2); Hypertension (2); Insulin resistance (2); male infertility (2); neurological disorders (2); Parkinson’s (2); Stroke (2); thrombosis (2); Abdominal obesity (1); adenocarcinoma (1); amyotrophic lateral sclerosis (1); Astigmatism (1); Ataxia (1); B cell lymphoma (1); Bartter syndrome type 4a (1); Bladder Cancer (1); Cerebellar hypoplasia (1); cognitive decline (1); colitis (1); colon polyp (1).
A further 32 diseases each share a sentence with LRP8 in 1 paper.